HIF1A (hypoxia inducible factor 1 subunit alpha)
Diseases named in the same sentence as HIF1A in open-access papers (continued):
Sharing a sentence is not in itself a finding about the gene and the disease.
diabetes (continued). "Surprisingly, we found decreased collagen deposition in both diabetes-exposed Hif1a+/− and Wt and in unexposed Hif1a+/− LVs when compared to Wt." (PMID 29753320, 2018). "In contrast to increased apoptosis in both diabetes-exposed Hif1a+/− and Wt, the number of F4/80+ infiltrating macrophages was significantly increased only in the LV of the diabetes-exposed Wt heart." (PMID 29753320, 2018). "CX43 phosphorylated at serine 368 (pCX43) was significantly reduced in the diabetes-exposed Hif1a+/− offspring compared to other groups." (PMID 29753320, 2018). "We found a decreased number of embryos per litter and increased incidence of heart malformations, particularly atrioventricular septal defects and reduced myocardial mass in diabetes-exposed Hif1a+/− mice compared to wild type (Wt) littermates." (PMID 29753320, 2018). "We found increased apoptosis in the RV and LV myocardium, and in the septum of both Hif1a+/− and Wt diabetes-exposed offspring." (PMID 29753320, 2018). "VEGFA levels in the coronary vessels were increased by the combination of Hif1a haploinsufficiency and diabetes exposure." (PMID 29753320, 2018). "Body weight was decreased in both Wt and Hif1a+/− offspring exposed to maternal diabetes, whereas the heart weight was lower in Wt mice at 12 weeks of age." (PMID 29753320, 2018). "In contrast to the levels of Vegfa mRNA in the LV, VEGFA expression in the blood vessel wall was significantly higher in diabetes-exposed Hif1a+/− than in Wt hearts." (PMID 29753320, 2018). "•Pharmacologically activating HIF-1α or increasing succinate concentrations restores the hypoxic response and improves functional recovery post-ischemia in diabetes." (PMID 30175272, 2018). "We recently discovered that rHDL rescues diabetes-impaired angiogenesis through its ability to increase HIF-1α stability and VEGFA production." (PMID 30206364, 2018). "In our previous study, deletion of Hif1a+/− in combination with maternal diabetes was shown to lead to an increased incidence of congenital cardiac defects." (PMID 29753320, 2018). "To extend our previous study on the effects of global heterozygous deletion of Hif1a and maternal diabetes exposure on heart development in embryos, we analysed the heart of the adult offspring in the same experimental paradigm." (PMID 29753320, 2018). "The relative gene expression of podocin (Nphs2), a marker for podocyte damage, was significantly elevated only in the diabetes-exposed Hif1α+/− renal cortex." (PMID 28774305, 2017). "HIF‐1α dysfunction under some pathologic conditions, such as diabetes, attenuates SDF‐1 up‐regulation and then impairs ischaemic angiogenesis 35, 36, while enhancing HIF‐1α expression 37, and/or its stabilization 38 can improve diabetic angiogenesis." (PMID 28374486, 2017). "Diabetes induction resulted in renal hypoxia as observed by the lower levels of HIF-1α found in kidneys of streptozotocin treated rats." (PMID 29270392, 2017). "In our study, consistent with previously published data, VEGFA expression was significantly increased in the glomerulus of diabetic Hif1α+/− compared to the diabetic Wt, indicating a faster progression of renal dysfunction in diabetes." (PMID 28774305, 2017). "Our partial deficiency Hif1α model provides the first model that tests in vivo the function of HIF-1α in the development and progression of diabetes-induced renal damage." (PMID 28774305, 2017). "More specifically, it has been reported that diabetes attenuates the HIF-1α mediated cardioprotection against IR injury." (PMID 29209228, 2017). "Our study showed that metformin, a first-line regimen of type 2 diabetes mellitus, had the potential to synergize with cisplatin to induce higher pro-apoptotic and anti-proliferative activity, through inhibition of NF-κB/HIF-1α axis in OSCC cells." (PMID 27762347, 2016). "HIF-1α activity is suppressed in diabetics due to the high-glucose levels and, as a result, impairs wound healing." (PMID 27830734, 2016).
diabetes (continued). "During the early stages of diabetes, HIF-1α and VEGF are signals that respond to the degree of tissue ischemia and hypoxia." (PMID 27057201, 2016). "Conversely, betaine treatment suppressed HIF-1α expression in the retinas of the STZ-induced diabetes rats (P<0.05)." (PMID 25891515, 2015). "A pressing question that follows these observations is how does diabetes inhibit HIF-1α expression and its translocation to the nucleus?" (PMID 25381014, 2015). "Betaine treatment attenuated this increase in VEGF and HIF-1α expression via suppression of diabetes-induced Akt activation in the retinas of the diabetic rats." (PMID 25891515, 2015). "With regard to the last notion, we have demonstrated that the protein expression of importin α1 and its binding to HIF-1α were markedly reduced as a function of diabetes." (PMID 25381014, 2015). "STZ-induced diabetes rats exhibited an increased number of HIF-1α-positive cells in the retinas, compared with those of the control group (P<0.05)." (PMID 25891515, 2015). "High glucose concentrations of 7–8 mmol/L, and concentrations up to values frequently reached in diabetes, again increased HIF1A transcript level." (PMID 25602014, 2015). "Previous studies have examined the involvement of HIF-1α in the development of obesity-induced diabetes by using genetically modified mice." (PMID 24705496, 2014). "In the present study, we examined the involvement of adipocyte HIF-1α in the development of obesity-induced diabetes in ahKO mice." (PMID 24705496, 2014). "To determine the effects of HIF-1α in adipocytes on the progression of obesity-induced diabetes, we prepared ahKO mice and recorded changes when the mice were fed a normal diet (ND) or a high-fat diet (HFD)." (PMID 24705496, 2014). "A study investigating the effect of HIF-1α on obesity and diabetes found the HIF-1α knockout mice manifested resistance to weight gain, while ameliorating IR." (PMID 25069390, 2014). "Our results highlight a critical link between diabetes, HIF-1α regulation, and cardiovascular dysfunction." (PMID 24502509, 2014). "Lower levels of HIF-1α protein were found in foot ulcer biopsies in patients with diabetes, in which hyperglycemia was shown to reduce the HIF-1α stability and function." (PMID 25464502, 2014). "The qPCR results revealed that the mRNA expression levels of HIF-1α in the severe diabetes group were significantly elevated compared with those in the control and mild diabetes groups (P<0.01)." (PMID 25371752, 2014). "In the present study, we prepared adipocyte-specific HIF-1α knockout (ahKO) mice and studied the effects of HIF-1α on the development of obesity-induced diabetes." (PMID 24705496, 2014). "In the next step, HIF-1α protein expression was analyzed in nuclear extracts from the LVs in order to understand the basis for the diabetes-induced changes in Hif1a+/- diabetic hearts." (PMID 24502509, 2014). "Cardiac-specific HIF-1α–overexpressing transgenic mice show cardiac protection from diabetes-induced defects in glucose metabolism and angiogenesis." (PMID 24502509, 2014). "Diabetes was induced by streptozotocin in wild type (Wt) and heterozygous Hif1a knock-out (Hif1a+/-) mice." (PMID 24502509, 2014). "In the current study, the expression of HIF-1α was enhanced in the blood of diabetes patients, while the levels of miRNA-18a were downregulated; thus, the results were in accordance with the previous studies." (PMID 25371752, 2014). "Endothelial HIF-1α was induced in diabetes-mimic milieus and diabetic kidneys, and the HIF-1α induction was inhibited by the presence of PCE." (PMID 24278186, 2013). "Patients with low level of hemoglobin and hyperglycemia in diabetes mellitus exhibited over-expression of HIF-1α and increased GLUT1 expression, respectively." (PMID 23927384, 2013). "NAC and ALP confer synergistic cardioprotection in diabetes via restoration of cardiac HIF-1α and HO-1 signaling." (PMID 23874823, 2013).
diabetes (continued). "Herein we evaluate the outcome of lipopolysaccharide- (LPS-) induced AKI in streptozotocin-induced diabetes, as well as the potential role of Hypoxia Inducible Factor (HIF-1α) in this condition." (PMID 23984430, 2013). "Hypoxia is the main regulator of HIF-1α expression and function in some conditions such as diabetes pathogenesis." (PMID 22844268, 2012). "As a result, this study showed that marked immunoreaction can be seen in the pancreas, liver and kidney with caspase-3, COX-1, COX-2, CSR, and HIF-1α in diabetes-induced rats." (PMID 22844268, 2012). "Retinal plasma extravasation, leukostasis and mRNA levels of B1R, iNOS, COX-2, VEGF receptor type 2, IL-1β and HIF-1α were significantly increased in diabetic retinae compared to control rats." (PMID 22470485, 2012). "Significantly, silencing of CHIP prevented degradation of HIF-1α under high glucose and hypoxia, emphasizing the putative relevance of CHIP-mediated degradation of HIF-1α in pathophysiological conditions such as diabetes." (PMID 21124777, 2010). "This review outlines the structural domains, activation mechanisms, and key target genes of HIF-1α, and further examines its involvement in diabetes-induced oxidative stress, impaired perfusion, endocrine dysregulation, and the imbalance of apoptosis and autophagy in testicular tissue." (PMID 40867634, 2025). "This highlights the central role of HIF-1α in the pathological process of diabetes." (PMID 40143173, 2025). "HIF1α is a core regulator of cellular responses to hypoxia, but its activation in chronic metabolic diseases (such as diabetes and obesity) may exacerbate oxidative stress and mitochondrial dysfunction." (PMID 40661082, 2025). "This review aims to explore the regulatory role of HIF-1α in diabetes-induced testicular damage." (PMID 40867634, 2025). "Based on these findings, we postulated that FG-4592 could exert a cardioprotective effect in diabetes by reducing oxidative stress injury through the enhancement of HIF-1α and UCP2 expression." (PMID 39920720, 2025). "HIF-1α drives metabolic reprogramming in both diabetes and cancer, promoting aerobic glycolysis." (PMID 41296433, 2025). "Consequently, better glucose control in individuals with diabetes increases HIF-1α protein levels and confers a wide range of benefits, some of which are partly mediated by HIF-1α." (PMID 41155523, 2025). "HIF-1α plays a central and multifaceted regulatory role in diabetes-induced testicular injury, encompassing various pathological processes such as oxidative stress, local hypoxia, impaired angiogenesis, testicular cell apoptosis, autophagy imbalance, and endocrine dysfunction." (PMID 40867634, 2025). "RAB11FIP3‐FL can promote the ubiquitination and degradation of HIF‐1α through the combination of NEDD4L and HIF‐1 α, thus inhibiting the proliferation, migration and tubular formation of vascular endothelial cells and suppressing the healing of diabetes wounds." (PMID 40758539, 2025). "Molecular docking was used to verify whether the main compounds of JCYSTLF inhibited diabetic kidneys senescence and improved dysfunctional autophagy via targeting HIF-1α to regulate autophagy." (PMID 38720731, 2024). "Interestingly, we showed that very early in diabetes and before the appearance of DR pathology, phase advances in pathways regulated by HIF1A were identified." (PMID 38039846, 2024). "That leads to reduced HIF1α protein in tissues in animal models of diabetes." (PMID 39769216, 2024). "Additionally, the negative impact on the size of the adrenal medulla in Hif1aCKO was further amplified by maternal diabetes, indicating an additive effect of Hif1a deletion and diabetes exposure." (PMID 38505753, 2024). "However, HIF-1α inhibitor 2-ME weakened the role of JCYSLTF in regulating autophagy in diabetic kidneys." (PMID 38720731, 2024).
diabetes (continued). "Elevated FA levels in diabetes can also impair cardiac Hypoxia-inducible factor 1-alpha (HIF-1α) accumulation, with a subsequent reduced cardiac adaptation to hypoxic conditions based on a model of insulin resistance in HL-1 cardiomyocytes, which affects cardioprotection." (PMID 39125850, 2024). "Furthermore, the regulation of ANGPTL4 expression by HIF-1α has been confirmed in various diseases, such as tumors, diabetes, and arterial sclerosis resulting from chronic intermittent hypoxia." (PMID 38992710, 2024). "ERK/HIF‐1α/ VEGF pathway was reported involve in angiogenesis in diabetes and myocardial ischemia." (PMID 38308197, 2024). "Previous research have reported that targeting HIF-1α could be an effective method to ameliorate kidney senescence in patients with diabetes." (PMID 38720731, 2024). "Moreover, HIF1A is downregulated in the skin of diabetes patients; HIF1A overexpression in ADSCs-derived extracellular vehicles can promote the healing rate and treatment of diabetes patients via activating the PI3K/AKT pathway." (PMID 37848931, 2023). "Diabetes was induced in Hif1a knockout and control mice by low doses of STZ treatment." (PMID 37072781, 2023). "Additionally, SRT1720 also suppressed HIF1α, GLUT1, and SNAIL expressions both in vivo and in vitro, indicating a role for SRT1720 in the prevention of diabetes-induced renal fibrosis via the SIRT1/HIF1α/GLUT1/SNAIL pathway." (PMID 37371668, 2023). "The size of the stellate ganglia of diabetic Hif1aCKO-Ai14 mice was significantly reduced compared to the control-Ai14, indicating negative combinatorial effects of Hif1a deficiency and diabetes." (PMID 37072781, 2023). "Therefore, the HIF1A inhibitor PX‐478 has the potential to be used as a therapeutic agent against diabetes and its complications, but its exact mechanism remains elusive." (PMID 37904700, 2023). "Although both diabetic control and mutant hearts had significantly more F4/80+ infiltrating macrophages than non-diabetic hearts, the combination of diabetes and the Hif1a-deficient sympathetic system resulted in the most extensive macrophage recruitment." (PMID 37072781, 2023). "Our findings also draw attention to testicular damage in diabetic patients and indicate that HIF-1α inhibitors may become a new direction for research and treatment of diabetes." (PMID 36778206, 2023). "Moreover, TRF also reduced retinal expression of VEGF (p < 0.001), IGF-1 (p < 0.001) and HIF-1α (p < 0.05) compared to vehicle-treated rats with diabetes." (PMID 37268913, 2023). "Our data showed a tendency towards the reduction in hif1a expression under diabetic conditions, and it is known that the repression of hypoxia-inducible factor-1 contribute to increased production of mitochondrial reactive oxygen species in diabetes." (PMID 37108202, 2023). "To examine the effects of PT hypoxia reflected as VHL-mediated HIF-1α stabilization in conditions of type 1 diabetes mellitus, we generated mice with deletion of Vhl in the early PT S1/2 segments by cross-breeding Vhlflox mice, termed control (con), with Sglt2cre mice, termed VHL∆PT." (PMID 37626062, 2023). "Thus, it seems that HIF-1α plays a critical role in maintaining β cells against autoimmune diseases, such as diabetes, stress, and viral infection." (PMID 37189396, 2023). "In our current study, we found that except for the apoptosis of ECs in spinal cord, diabetes could also induce the adverse microenvironment for angiogenesis with significantly inhibiting expressions of HIF-1α, VEGF, and ANG1 in spinal cord after SCI." (PMID 37215981, 2023).
diabetes (continued). "This is one of the first reports of the participation of the WWOX/HIF1A axis and the Warburg effect in the pathogenesis of diabetes, therefore further research is definitely needed, which could indicate the potential clinical use of the obtained information." (PMID 35328751, 2022). "This association might protect the NPDR patients from progression to the proliferative stage even after long-lasting diabetes because of elevating circulating HIF-1α Pro582Ser which is known to be resistant to hyperglycemia and hyperlipidemia." (PMID 35969320, 2022). "Notably, the chronic administration of PTS facilitated burn-wound healing in diabetes, facilitated by a significant reduction in diabetes-induced oxidative stress and the suppression of hypoxia-induced factor1α (HIF1α) activity." (PMID 36234852, 2022). "As HIF-1α has been involved in the regulation of metabolic processes and in the development of insulin resistance and diabetes, it may further contribute to the development and aggravation of the metabolic co-morbidities of OSA." (PMID 36079094, 2022). "In recent years, various types of HIF-1α inhibitors have been designed and synthesized and are expected to become a new class of drugs for the treatment of diseases such as tumors, leukemia, diabetes, and ischemic diseases." (PMID 35684364, 2022). "In addition, a recent report suggests that HIF-1α expression was increased in peripheral nerve fibers in a patient with diabetes." (PMID 36017378, 2022). "What is more, as one of the first we focus on the share of the WWOX/HIF1A axis in diabetes." (PMID 35328751, 2022). "Relatively little is known about HIF1α participation in the pathogenesis of diabetes." (PMID 35328751, 2022). "Glucose-induced inhibition of HIF-1α protein stability may also accelerate the deterioration of β cell function and speed progression to diabetes." (PMID 34875999, 2021). "Results of in vivo studies in experimental animal models might also reflect this dual role of HIF-1α in diabetes-related vascular damage." (PMID 34572324, 2021). "This suggests that strategies to improve the stability of HIF-1α, such as by blocking the interaction between VHL and HIF-1α, could be a promising strategy for the treatment of diabetes wound complications." (PMID 34099651, 2021). "Although absolute HIF-1α levels in diabetic kidney may remain unchanged or even increase, they are significantly lower relative to those in profound hypoxia." (PMID 33496820, 2021). "Finally, we studied NFAT5 as a biomarker of hypertonicity and HIF-1α as a biomarker of hypoxia conditions because both molecules are closely related to diabetes." (PMID 35046888, 2021). "Hence, these studies suggest that AGEs, RAGE and HIF-1α comprise an important pathway of influencing glucose metabolism in testicular cells during diabetes." (PMID 34262451, 2021). "The present study explored the influence of liraglutide on remotepreconditioning-mediated cardioprotection in diabetes mellitus along withthe role of nuclear factor erythroid 2-related factor 2 (Nrf2), hypoxiainducible factor (HIF-1α) and hydrogen sulfide (H2S)." (PMID 33656046, 2021). "However, there are some exceptions, e.g., elevated expression of HIF-1α was found in mesangial cells of renal glomeruli exposed to high glucose or isolated from animal models of diabetes." (PMID 34948094, 2021). "Translational control of HIF-1α via mTOR may be relevant in diabetes, as hyperinsulinemia inhibits mTOR signaling." (PMID 34426491, 2021). "In this study, we have demonstrated that tubular epithelial cells from diabetic patients and mice with experimental model of diabetes undergo a metabolic switch from FAO to glycolysis, and the underlying mechanism for this metabolic switch is likely involved in stabilization of HIF-1α." (PMID 32444604, 2020). "Simultaneously, the relationship among miR-1248, CITED2, HIF-1α, and diabetes was first reported." (PMID 32294623, 2020).